GRIN2A (glutamate ionotropic receptor NMDA type subunit 2A)
Diseases named in the same sentence as GRIN2A in open-access papers (continued):
Sharing a sentence is not in itself a finding about the gene and the disease.
depression (47 papers, 2009 to 2026). "Studies have shown the abnormal expression of GluN2A (encoded by the GRIN2A gene in 16p 13.2) due to GRIN2A gene hyper-methylation, which resulted in increased susceptibility to depression." (PMID 35456452, 2022). "Evidently, IPA unearthed a substantial number of genes, like Disc169, Syn370, Synpo71, Grin2a, Gria1, Foxo3, and many others which reportedly have been shown to be linked with depressive disorder, bipolar disorder and/or SSDs." (PMID 34362910, 2021). "Furthermore, some studies showed that miR-320a in the plasma of patients with depression targeted and regulated Grin2a, whereas a reduction in Grin2a levels caused a significant reduction in long-term potentiation (LTP) and impaired spatial learning and memory." (PMID 35562946, 2022). "Aberrant GRIN2A hypermethylation has been found in the hippocampus and prefrontal cortex in major depressive disorder." (PMID 38319733, 2024). "In this regard, only one study has found a hypermethylation of the GRIN2A gene body in the hippocampus and prefrontal cortex of post-mortem human tissue in depression, which has been attributed to overexpression of the GluN2A subunit." (PMID 32585886, 2020). "On the other hand, in the frontal cortex, BDNF deficiency, which occurs under chronic stress and is one of the leading causes of depression, also increased the density of GRIN1, GRIN2A and GRIN2B genes in the early stages of development." (PMID 32585886, 2020). "The expression level of miR-137 is significantly lower in the brain in post-stroke depression rats, and delivery of miR-137 into the brain improves their behavioral performance by suppressing the expression of Grin2A." (PMID 31736707, 2019). "Up-regulation of GRIN2A was observed in dorsolateral prefrontal cortex of female major depressive disorder cases, which is consistent with our results." (PMID 26690197, 2015). "The precise epigenetic regulation of GRIN3A is unknown, but DNA methylation in the promoter of glutamate ionotropic receptor NMDA type subunit 2a (GRIN2A), which is another subunit of NMDA, is strongly associated with major depressive disorder in humans." (PMID 35144563, 2022). "Moreover, aberrant DNA methylation at the GRIN2A locus was described in patients with major depression." (PMID 29089052, 2017). "Also, in patients with major depressive disorder altered DNA methylation had been reported for three distinct CpG sites along the GRIN2A promoter." (PMID 29089052, 2017). "Interestingly, some of the linear dose-response DEGs have been implicated in transmission and plasticity (GRIN2A, GAD2), depression and antidepressant effect (DDIT4, GAD2) anxiety and stress responses (ADCYAP1R1), WNT signalling (FRZB), neurogenesis (ARHGEF39) and hippocampal volume (ANKRD37)." (PMID 39055655, 2024). "NR2A (Grin2a) is a subunit of the ionotropic glutamate receptor NMDA receptor, which is significantly upregulated in the brain of patients with depression and suicide." (PMID 35562946, 2022). "Five important depression targets identified using the network map (GRIN2B, GRIN2A, DRD2, SLC6A4, and MAOA) and twenty-one related active compounds were selected for molecular docking." (PMID 33746756, 2021). "Also, NMDA (N-methyl-D-Aspartate) receptors Grin2a (Glutamate receptor ionotropic, NMDA 2A) and Grin2b (Glutamate receptor ionotropic, NMDA 2B) play key role in the pathology of mood disorders and their polymorphisms could be associated with depression." (PMID 25423262, 2014). "Additional examples include schizophrenia for RELN, GluR6, GRIN2A, GRIN2B, and CNTNAP2, childhood absence epilepsy for GABRB3, ADHD and depression for 5-HTT, and major depression for TPH2." (PMID 23935565, 2013).
Anxiety (39 papers, 2011 to 2026). Intense feelings of nervousness, tension, or panic often arise in response to interpersonal stresses. "Especially in dominant female mice compared to their submissive counterparts, genes involved in modulating fear response and anxiety (e.g., Cacna1e, Nlg2, Tnr, Grin2a, and Grin2b) were up-regulated." (PMID 34490254, 2021). "Knockout of GRIN2A and GRIA1 causes a decrease in anxiety in mouse models." (PMID 34763096, 2022). "GRIN2A and GRIA1 are two important glutamate receptors involved in the function of the sensorimotor cortex and also involved in anxiety." (PMID 34763096, 2022). "Grin2a KO (but not Het) mice had reduced ratios of center/margin distance traveled (by ~30%) relative to WT animals (p = 0.0438), suggesting anxiety-like behavior." (PMID 36914641, 2023). "Additionally, mutant mice lacking Grin2a expression do not exhibit anxiety-related behavior after restraint stress." (PMID 37239367, 2023).
melanoma (39 papers, 2012 to 2026). A malignant, usually aggressive tumor composed of atypical, neoplastic melanocytes. "Nevi most often harbored canonical MAPK-pathway mutations in BRAF and NRAS, as well as in GRIN2A, while melanomas, along with BRAF and NRAS, frequently carried additional driver alterations in ARID1A, ARID2, CDKN2A, and PTEN." (PMID 41516405, 2026). "As the focus of GRIN2A-related somatic variants was on melanoma samples, GRIN2A gene expression was compared for different tumor tissues including skin cutaneous melanoma tissues and paired normal tissues." (PMID 40565021, 2025). "It was therefore surprising and unexpected to find that GRIN2A is frequently mutated in tumor samples, especially in melanomas." (PMID 40565021, 2025). "Recently, a high prevalence of somatic mutations (W372X, Q891X, R920K, and W1271X) in GRIN2A, a subunit of NMDARs, has been identified in malignant melanoma patients." (PMID 40236296, 2025). "In melanoma, the expression of GRIN2A (Glutamate Ionotropic Receptor NMDA Type Subunit 2A) was reported to be mutated in 33% of melanoma samples." (PMID 36817470, 2023). "Previous whole-exome sequencing has demonstrated that melanoma tumors harbor mutations in the GRIN2A gene and patients with GRIN2A mutations have more aggressive disease." (PMID 36768862, 2023). "This indicates that the GRIN2A mutation acts as a proto-tumor in melanoma, given the fact that the mutation of GRIN2A in melanoma cells increases the proliferation of melanoma cells." (PMID 36817470, 2023). "Intriguingly, disrupting mutations in the GRIN2A gene are frequent in melanoma, and they are associated with bad prognosis." (PMID 37173906, 2023). "In cases of ICI-induced autoimmune encephalitis, there are potential interactions between N-methyl-D-aspartic acid (NMDA) receptor subunits encoded by GRIN2A (Glutamate Ionotropic Receptor NMDA Type Subunit 2A), which is also commonly mutated in melanoma." (PMID 34201529, 2021). "Variants of GRIN2A were associated with the protective effect of coffee against PD, and mutations of GRIN2A in melanoma correlate with decreased survival." (PMID 32210791, 2020). "Focal somatic pathogenic alterations occurred in B2M and GRIN2A genes encoding transmembrane proteins, the latter gene being mutated in metastatic glioblastoma and frequently, in melanoma." (PMID 32680567, 2020). "The p.R1288H somatic mutation in GRIN2A has been extensively reported in various solid cancers, including melanoma, lung and colorectal cancer." (PMID 32014051, 2020). "NMDA receptors are expressed on the surface of melanocytes and are coded by the gene GRIN2A, which tends to be highly mutated in patients with melanoma." (PMID 30217214, 2018). "In terms of NMDARs and their subunits, mutations frequently appear in the NR2A gene, GRIN2A, correlating with decreased survival of melanoma patients." (PMID 29966365, 2018). "A preliminary study of matched whole exome sequencing of melanomas and matched normals indicates that GRIN2A was frequently mutated in 14 specimens, and subsequent analysis of over 100 samples showed it to be mutated in 33% of cases." (PMID 25393105, 2014). "Previous whole-exome sequencing has demonstrated that melanoma tumors harbor mutations in the GRIN2A gene." (PMID 24455489, 2014). "NMDARs are best known for their roles in the brain; hence, the finding of GRIN2A mutations in melanoma had been unexpected." (PMID 24455489, 2014). "The true frequency of GRIN2A mutations in melanoma remains uncertain, but our results support the high prevalence of GRIN2A mutations in metastatic melanoma." (PMID 24455489, 2014). "Well-characterized melanoma cell lines with known mutations, such as those described in this manuscript, will be valuable tools to examine the mechanisms of action and consequences of specific GRIN2A mutations in melanoma tumors." (PMID 24455489, 2014).
melanoma (continued). "The existence of mutations in glutamate receptors was described in prior exome sequencing studies, and our data not only confirmed that GRIN2A was mutated in melanoma (5 out of 28 cases) but also showed that GRIN2B was recurrently mutated." (PMID 25393105, 2014). "Further work in this area will be required to clarify if synonymous GRIN2A mutations play a role in melanoma biology." (PMID 24455489, 2014). "Our results are in agreement with the seminal whole-exome sequencing work, where non-synonymous mutations in GRIN2A were found in 26% of melanoma samples." (PMID 24455489, 2014). "Mutations in GRIN2A have been reported in up to a third of melanoma samples, although there is wide variation between studies and no data on their clinical relevance." (PMID 24455489, 2014). "Sequencing of melanoma samples identified the glutamate receptor subunit GRIN2A as the most frequently mutated gene." (PMID 25593989, 2014). "Recently, the exome sequencing analysis revealed that GRIN2A (encoding the ionotrpic glutamate receptor (N-methyl D-aspartate) subunit 2A) was mutated in 33% of melanoma tumors, clearly indicating the involvement of glutamate signaling in melanoma development." (PMID 22807686, 2012). "Previous whole-exome sequencing studies have shown melanoma tumors with GRIN2A mutations." (PMID 38333293, 2024). "A similar study found that the mutation of GRIN2A was detected in 25% of melanoma samples." (PMID 36817470, 2023). "It has been reported that 11 somatic mutations in GRIN2A were involved in melanoma." (PMID 32241263, 2020). "Furthermore, GRIN2A was shown to be a tumor suppressor in melanoma as loss of its activity resulted in uncontrolled cell proliferation." (PMID 29966365, 2018). "Furthermore, PREX2 and GRIN2A mutations were significantly more prevalent in melanomas with mitosis [p = 0.042; OR = 4.0 (1.0–15.4) and p = 0.023; OR = 6.2 (1.3–29.5), respectively]." (PMID 28356599, 2017). "Further studies will need to address whether mutations of GRM3 or GRIN2A are the reason for tumorigenicity or aggressiveness in melanoma cells." (PMID 28522871, 2017). "Overall, patients with non-synonymous GRIN2A mutations had faster progression of melanoma from skin lesions to the involvement of lymph nodes (P = 0.04) or distant organs (P = 0.012), and shorter overall survival (P = 0.013) compared with patients with non-mutated GRIN2A." (PMID 24455489, 2014). "Our findings suggest for the first time, to our knowledge, that GRIN2A mutations may drive melanoma progression." (PMID 24455489, 2014). "Mutant GRIN2A inhibits the tumor-suppressive function of the wild-type GRIN2A, promoting melanoma cell survival." (PMID 40236296, 2025). "The SMGs identified in our mouse models included well-described melanoma and leukemia oncogenes and tumour suppressors (Muc4, Pten, Grin2a, Dnmt3a, Npm1 and Flt3) reinforcing the WES validation and the subsequent filtering of SMGs." (PMID 39223638, 2024). "By querying the TCGA (The Cancer Genome Atlas Program) pan-cancer atlas studies, it was found that GRIN2A is altered in 5% of all cancers, with melanoma, lung, colorectal, bladder, and breast cancer having the greatest prevalence of alterations." (PMID 36768862, 2023). "Next generation sequencing found that GRIN2A mutation was related to CLDN18.2 expression in advanced gastric SRCC, which was frequently found in melanoma and induced the loss of tumor suppressor function." (PMID 35811317, 2022). "The driver oncogene of deep penetrating melanoma is GRIN2A (N-methyl-D-aspartate receptor glutamate ionotropic receptor NMDA type subunit 2A), while the nevus-like melanoma is characterized by mutations of the lipid/AKT signaling pathway." (PMID 35628196, 2022). "NMDAR is expressed on melanocytes, and GRIN2A gene, which encodes the NMDAR subunit GluN2A, is highly mutated in melanoma patients." (PMID 32796758, 2020).
melanoma (continued). "In adition, GRIN2A and RAC1 mutations were also associated with chronically sun-exposed melanomas [p = 0.011; OR = 5.9 (1.5–23.2) and p = 0.026; OR = 3.2 (1.1–9.2), respectively]." (PMID 28356599, 2017). "Mutations in GRIN2A, GATA3 and KDM6A which have been identified in melanoma, breast cancer and recently identified as a candidate driver of pancreatic carcinogenesis, respectively, were only identified within the EUS FNA cytology smear specimens." (PMID 27203738, 2016). "GRM3 and GRIN2A/2B alterations were also frequently observed in the tumors sequenced herein, suggesting the importance of glutamate mediated transduction in melanoma." (PMID 25393105, 2014). "GRIN2A encodes the regulatory GluN2A subunit of the glutamate-gated N-methyl-d-aspartate receptor (NMDAR), involvement of which in melanoma remains undefined." (PMID 24455489, 2014). "Here, we sequenced coding exons of GRIN2A in 19 low-passage melanoma cell lines derived from patients with metastatic melanoma." (PMID 24455489, 2014). "Nineteen low-passage melanoma cell lines, derived from 19 patients with metastatic melanoma, were used in this study to sequence coding exons of GRIN2A, together with their flanking intronic regions." (PMID 24455489, 2014). "The GRIN2A gene encodes the regulatory GluN2A subunit of the glutamate-gated N-methyl-d-aspartate receptor (NMDAR), and its involvement in melanoma remains unclear." (PMID 38333293, 2024). "Several studies show how mutants of GRIN2A result in malignant melanoma." (PMID 35646664, 2022). "Additionally, high levels of extracellular glutamate may be associated with glutamate ionotropic receptor NMDA type subunit 2A gene (GRIN2A) mutations, frequently found in melanoma tumors." (PMID 34068618, 2021). "The ionotropic glutamate receptor GRIN2A and the metabotropic glutamate receptor GRM3 were found to be mutated in 25% and 16%, respectively, of melanoma samples, but without recurrent mutations for GRIN2A and with only a small percentage of recurrent GRM3 mutations." (PMID 30987166, 2019). "Considering that there is currently no reliable genetic biomarker that predicts melanoma progression, GRIN2A mutation testing may offer valuable prognostic information." (PMID 24455489, 2014). "In addition, both GRIN2A and TECTA were among the most intolerant genes according to the RVIS (Residual Variation Intolerance Score), indicating that the variants within these genes are under natural selection and may be more likely to influence melanoma." (PMID 32241263, 2020). "Our in silico significance and proximity analysis of 28 paired cases (13 WGS and 15 targeted cases) identified known (e.g., BRAF, NRAS, CDKN2A, and GRIN2A) and novel (e.g., EPHA3, GRIN2B, and ASXL3) genes involved in melanoma." (PMID 25393105, 2014). "In addition, the overexpression of the mutant GRIN2A in 31T and SK-Mel-2 melanoma cell lines increased the migration compared to both wild-type GRIN2A, whereas the use of a specific NMDAR2A (GRIN2A) antagonist, TCN-213 reversed the effect mentioned." (PMID 36817470, 2023).
Intellectual disability (32 papers, 2012 to 2026). "Studies have shown that missense mutations in GRIN2A are frequently observed in patients with severe developmental disorders and intellectual disabilities, whereas protein-truncating variants tend to be less common." (PMID 39596430, 2024). "For instance, individuals with missense variants in the TMD + Linker domain of GRIN2A subunits present with more severe developmental delay (DD) and intellectual disability (ID) phenotypes compared to those with variants in the ATD + LBD regions." (PMID 39596430, 2024). "GRIN2A has also been linked to a form of benign epilepsy, co‐occurring with intellectual disability." (PMID 30378284, 2018). "GRIN2A gene mutation has been observed in some cases of EAS, and it might be associated with intellectual disabilities and learning difficulties." (PMID 40727434, 2025). "Individuals with a severe developmental disorder and intellectual disabilities are more prone to the missense mutations in GRIN2A rather than the protein-truncation variants." (PMID 39596430, 2024). "Mutations in GRIN1 (which encodes the GluN1 subunit), GRIN2B (GluN2B), and GRIN2D (GluN2D), expressed during embryonic development, display more severe clinical phenotypes, including severe intellectual disability and developmental delay, than GRIN2A (GluN2A) mutations." (PMID 32197322, 2020). "For 177 of all 248 individuals with (likely) pathogenic variants in GRIN2A, we obtained detailed information about presence or absence of ID/DD and ranked severity of intellectual disability into five categories (refer to the ‘Materials and methods’ section)." (PMID 30544257, 2019). "Notably, it is missense mutations rather than protein-truncating variants in GRIN2A that are associated with risk of severe developmental disorder and intellectual disabilities." (PMID 37736757, 2023). "While some GRIN2A patients have severe intellectual disabilities, roughly half have no intellectual impairment." (PMID 39535073, 2025).
Alzheimer disease (30 papers, 2011 to 2025). A progressive, neurodegenerative disease characterized by loss of function and death of nerve cells in several areas of the brain leading to loss of cognitive function such as memory and language. "Among the predicted drugs, memantine and memantine hydrochloride were classical drugs for Alzheimer’s disease that target GRIN2A." (PMID 39650656, 2024). "On the other hand, seizures caused by GoF mutations in the GRIN2A gene, encoding for the GluN2A subunits of NMDA receptors, can be treated with memantine, an NMDA receptor antagonist that was previously used in the treatment of Alzheimer’s disease." (PMID 38003469, 2023). "A reported decrease in GRIN2A plays some roles in calcium signaling and neuro-degradation in Alzheimer’s disease." (PMID 35741665, 2022). "In an integrated bioinformatics analysis of AD, GRIN2A is a hub gene for the miRNA interaction network, and its expression is decreased in AD samples, suggesting that GRIN2A plays some roles in calcium signaling and neurodegeneration in Alzheimer’s disease." (PMID 35741665, 2022). "Grin2a expression was previously linked to HDAC2 activity and H4K12acetylation in animal models of Alzheimer’s disease." (PMID 29089052, 2017). "High-priority targets include established therapeutic genes such as IGF1, for which mecasermin represents an existing FDA-approved treatment, and GRIA1/GRIN2A, which are targeted by memantine and other glutamate receptor modulators currently used in Alzheimer’s disease management." (PMID 41155297, 2025). "These genes include CACNA1C, LRP1, PLCB2, GRIN2A, and NMUR2, which are involved in pathways such as Alzheimer’s disease, long-term potentiation, calcium signaling, and transmission across chemical synapses." (PMID 29184056, 2017).